CXCR3 (C-X-C motif chemokine receptor 3)
Diseases named in the same sentence as CXCR3 in open-access papers (continued):
Sharing a sentence is not in itself a finding about the gene and the disease.
infection (continued). "CD28 expression was upregulated from 4 to 12 weeks and CXCR3 expression was upregulated at 8 and 12 weeks post-infection." (PMID 23448601, 2013). "We found strong upregulation of CXCR3 and its specific chemokine ligands as early as Day 4 post-infection in both the ileum and mesenteric lymph nodes (MLN)." (PMID 24130498, 2013). "Defective IL-12 responses in the CXCR3 KO strain were infection dependent, because parasite antigen stimulated equivalent amounts of IL-12 in noninfected WT and KO splenocytes." (PMID 24130498, 2013). "Although Th1 effectors depend upon CXCR3 to reach the site of infection, inflammatory monocytes require chemokine receptor CCR2 for optimal trafficking." (PMID 24130498, 2013). "In this study, we demonstrate a central role for chemokine receptor CXCR3 in empowering Th1 trafficking to the small intestine, in turn enabling inflammatory monocyte activation and concomitant control of infection." (PMID 24130498, 2013). "To study the potential of NK cells to migrate to infected peripheral tissues upon MPXV infection, we assessed the expression of chemokine receptors CXCR3, CCR5, CCR6, and CCR7 on each NK cell subset." (PMID 24147080, 2013). "In our model we did not see a dependence on CXCR3 for NK cell recruitment, as NK cells appeared to lose CXCR3-GFP expression over the course of infection, and production of NK cell IFN-γ was equivalent in WT and KO mice." (PMID 24130498, 2013). "We found in this report a higher frequency of CXCR3+ among CD4 T cells in the acute DENV-infection, while a similar proportion of the CXCR3+ among CD8 T cells was detected in DENV-infected patients as compared to controls." (PMID 22815692, 2012). "In particular, we showed that IFN-γ-dependent chemokines (CXCL9/10) were strongly induced, as shown by others, and increased during the course of infection, as well as their receptor CXCR3." (PMID 22457760, 2012). "There is also constitutive, although lower, expression of CXCR3 by CNS resident microglia, which remains unchanged following infection." (PMID 23209401, 2012). "Multiple studies have demonstrated the role of CXCR3 and its ligands in the migration of activated T cells during Th1 immune responses including to sites of infection." (PMID 23209401, 2012). "By binding to a commonreceptor, termed CXCR3, the three chemokines have the ability to attract subsets ofcirculating leukocytes to sites of infection and/or inflammation." (PMID 21533215, 2011). "During inflammation, IFN-γ induces plasmablasts to express the chemokine receptor CXCR3, promoting their migration into inflamed tissues and thereby maximising antibody production at sites of infection." (PMID 20174609, 2010). "Concomitantly, we observed increased expression levels of the inflammatory chemokine receptors CCR5 and CXCR3 by Ly49s3+ bone marrow NK cells, as compared to Ly49s3− NK cells, suggesting involvement of Ly49s3+ NK cells in the early phase of infection." (PMID 21179539, 2010). "The increased activation and infection of CXCR3+ Tfh in S4/5 of AHI together with increased virus deposition on the FDC may contribute to seeding of HIV-1-infected cells in the follicle at this time." (PMID 39932316, 2025). "Thus, unbiased analyses revealed phenotypic differences in SARS-CoV-2-specific B cells in the peripheral blood post-infection and post-vaccination, including enrichment of CXCR3+CD21+ BSM post-infection." (PMID 40964019, 2025). "Our results suggest that CXCR3 expression affords two key characteristics incMBCs that may contribute to enhanced mucosal protection post-infection." (PMID 40964019, 2025). "While Cxcl9, Cxcl10 and Cxcl11 were upregulated, CXCR3 was downregulated post PCN033 infection." (PMID 41295668, 2025). "Thus, CXCR3+CD21+ SARS-CoV-2-specific BSM with BRM features were enriched in upper respiratory tract lymphoid tissue after infection compared to vaccination." (PMID 40964019, 2025).
infection (continued). "Because CXCR3+ B cell frequency in MS is positively correlated with EBV viral load and the virus can induce B cell CXCR3 mRNA and protein expression, infection may promote ABC trafficking to the CNS." (PMID 40359016, 2025). "CXCR3 may facilitate the migration of NK and T cells to the tissue during infection, especially in a type 1 interferon-rich environment." (PMID 39000234, 2024). "In addition, we measured the expression levels of CXCR3, a marker known to facilitate homing to inflamed lung mucosae during infection via CXCL9 and CXCL1039,43,44." (PMID 37573434, 2023). "To determine whether CXCR3−/− mice had more severe PR8.p25 infections that contributed to their p25-specific CD4+ T cell responses, we monitored the weights of the infected CXCR3−/− and WT mice." (PMID 37896952, 2023). "The frequencies of Th17 (CCR6+CXCR3-) cells were significantly increased in patients already on day 2 compared to the healthy controls and Th17 responses remained significantly elevated until day 7 of infection." (PMID 37809062, 2023). "Indeed, CCR5- and CXCR3-mediated inflammatory chemotaxis of CD8+ T cells to infected LNs has been demonstrated in various infection models, including HIV." (PMID 37205767, 2023). "Cxcr3 guides T cells to LN periphery to support effector T cell differentiation during infection." (PMID 36472588, 2023). "Furthermore, effector CD8+ T cells upregulated CXCR3 expression on their cell membranes following infection with a variety of intracellular pathogens." (PMID 37761328, 2023). "CXCR3 and its ligands are responsible for recruiting macrophages to sites of injury/infection." (PMID 36271843, 2023). "Since previous studies support IL10 as a key player in the establishment and perpetuation of HIV persistence, the upregulation of IL10 in CXCR3+TFH may result in enhanced persistence of HIV after infection." (PMID 35619703, 2022). "Thus, we conclude that activation of the chemokine receptor CXCR3 plays an important role in mobilizing BRM cells to sites of infection." (PMID 35349789, 2022). "YFP+ CXCR3+ CD4+ T cells could be early immune responders that are able to migrate to areas of infection where they can rapidly induce a TH1 response." (PMID 35092032, 2022). "The CXCL10/CXCR3 axis plays a crucial role in disease pathogenesis upon CVA2 infection." (PMID 35604176, 2022). "CXCR3+ TH1-like TFH cells, along with populations of CXCR5+CCR6+ unswitched classical and activated MBCs, were found among the most significant populations associated with increased risk of infection." (PMID 34128836, 2021). "Decidua from 10 ZIKV-infected dams obtained 16-56 days post infection at third (n=9) or second (n=1) trimester showed a significant reduction in frequency of activated, CXCR3+, and/or Granzyme B+ memory CD4+ and CD8+ T lymphocytes and γδ T compared to normal decidua." (PMID 34394129, 2021). "Although no significant change in CXCR3 expression was observed between 1.5 and 9 months post-infection, we did find an association between the level of CXCR3 expression at 1.5 months post-infection and the fold decline in MuV-specific T-cell frequencies." (PMID 34960178, 2021). "Thus, the high expression of CXCR3 and low levels of CXCR4 at 1.5 months post-infection associate with the decrease in T-cell frequencies, which implies migration to the inflammation site and bone marrow at 1.5 month." (PMID 34960178, 2021). "Indeed, CXCR3 expression at 1.5 months post-infection did show that the higher the expression of the homing marker, the stronger the decline in T-cell frequencies." (PMID 34960178, 2021). "A decrease in CXCR3 indicates either that T cells are less able to home to the site of infection, or that there is more inflammation in PLWH during SARS-CoV-2 infection and therefore more homing of the CXCR3+ CD8 T cells to tissues so that the fraction of CXCR3+ cells left in the blood decreases." (PMID 34608862, 2021).
infection (continued). "Similarly, the overrepresentation of BIOCARTA_NKT_PATHWAY, with the upregulation of Cxcr3 (Th1-specific chemokine receptor, suggests that there is active signaling of Th1 response cells at the site of the infection." (PMID 34281214, 2021). "Therefore, the reduced expression of CXCR3 seen on Ag-specific CD4+ T cells from pMT-10 mice overexpressing IL-10 in early stages of infection likely plays a crucial role in the delayed migration of these cells into the lung parenchyma." (PMID 34554927, 2021). "The expression of both CCR7 and CXCR4 increased significantly between 1.5 and 9 months post-infection for T cells specific for all three epitopes (p = 0.0002 and p = 0.0137, respectively), while the expression of CXCR3 remained stable between these two timepoints." (PMID 34960178, 2021). "Interestingly, the frequency of T-bet+ CD8+ cells in PBMCs of old RMs decreased significantly after infection; in contrast, the proportion of CXCR3+ CD8+ cells increased." (PMID 34471088, 2021). "As CD8+ T cells interacted with plasmacytoid dendritic cells during infection by T. cruzi, we suggest that anti-CXCR3 treatment lowers the quantity of plasmacytoid dendritic cells, which may contribute to impair the prime of CD8+ T cells." (PMID 32574175, 2020). "CXCR3 is closely related to the severity of disease infection." (PMID 33208100, 2020). "Furthermore, CXCR3 expression was evaluated in the spleen and lymph nodes on days 5, 10, 15, 20, and 30 after infection." (PMID 32574175, 2020). "CXCR3 on monocytes has been shown to be upregulated during infection and inflammation, suggesting that either the endogenous decidual monocytes already present upregulated their CXCR3 expression or there was an influx of new CXCR3+ monocytes on LPS treatment." (PMID 32528468, 2020). "In spite of our result, the role of CXCR3 in CD4+ T cells migration has been shown in infection by Plasmodium chabaudi, however, in our model we believe that others chemokine might be involved in CD4+ T cells migration to spleen." (PMID 32574175, 2020). "On the same day of infection, we treated the mice with anti-CXCR3 antibody." (PMID 32574175, 2020). "Furthermore, ZIKV-specific effector CD8 T cells have been found to upregulate CD11a and CD49d, which, besides being markers of previous antigen encounter, together with CXCR3 are known to direct CD8 T cells to sites of infection including the CNS." (PMID 32973802, 2020). "Thus, we performed the in vivo cytotoxicity of specific CD8+ T cells on day 12 after infection and observed that those cells from the Isotype control mice had almost 50% of cytotoxicity, while the percentage in the anti-CXCR3 group was 27%." (PMID 32574175, 2020). "Indeed, flow cytometry revealed a significant reduction in the percentage of CXCR3+CD8+ T cells in the brain 8 days after PbA infection when mice had received BCG 30 days before." (PMID 33316929, 2020). "CXCR3 participate in CD8+ T cell activation during infection with T. cruzi." (PMID 32574175, 2020). "During infection with parainfluenza, CXCR3 guides CD4+ T cells to the lungs." (PMID 32574175, 2020). "In line with their discovery, we find that CXCR3+ Tregs produce more IL‐10 than CXCR3− Tregs, implying that CXCR3+ Tregs may secrete IL‐10 to modulate the infection‐induced inflammation." (PMID 33014369, 2020). "Interestingly, we observed that the number of pDCs in the spleen and lymph node decreased after infection and treatment with anti-CXCR3 antibody when we compared to the isotype control group; also, pDCs expressed CXCR3 receptor on the surface after infection." (PMID 32574175, 2020). "Similarly, epicutaneous VV infection in the ear results in a localized infection with CXCR3-dependent and infection site-restricted recruitment of virus-specific CD8+ T cells." (PMID 32433493, 2020).
infection (continued). "Together, these findings suggest that Foxp3+ Tregs, like effector CD4+ T cell subsets, respond to local cytokines by modifying their chemokine receptors including CXCR3 to promote their migration to sites of inflammation and infection where they function to suppress immune responses." (PMID 30915078, 2019). "Moreover, our work places CXCR3 as a powerful molecule able to address specific cell to target tissue of infection and, therefore, to be included as a key requirement for design of vaccines against intracellular pathogens." (PMID 31356587, 2019). "After infection with lymphocytic choriomeningitis virus, CXCR3 deletion leads to impaired production and localization of effector CD8+ T cells, and CXCL10 precisely coordinates effector CD8+ T cells to the site of Toxoplasma gondii, another intracellular eukaryotic pathogen." (PMID 31440475, 2019). "Our results indicate that CD103+ DCs have an additional, non-redundant function during the recruitment of pTregs to sites of infection, as we find that the induction of CXCR3 expression in pTregs during their priming in the LNs is highly dependent on this DC subset." (PMID 31188899, 2019). "Similar results were observed during infection by virus and during anti-CXCR3 treatment." (PMID 31356587, 2019). "CXCR3 expression is considered critical for recruitment of T-cells to site of infection." (PMID 31681272, 2019). "At 20 days after infection, the quantification of parasite load in spleen by real time qPCR supported that trend in the treated group, showing that the number of parasites in the spleen of anti-CXCR3-treated vaccinated and challenged mice (ASP2+αCXCR3+T." (PMID 31356587, 2019). "However, during high-dose infection, our results suggest a greater importance for CXCR3 in NK cell recruitment to the DLN, as CXCR3−/− NK cell recruitment was reduced." (PMID 29719539, 2018). "Interestingly, we also found a small subpopulation of CD14+ monocytes with distinctly higher expression of previously unreported markers (CCR4, CXCR3, and CCR6) that also associated with the acute phase of infection." (PMID 30150281, 2018). "Overall, our data suggest that the severity of IAV infection dictates the localization and number of NK cells in lymphoid tissue and the site of infection and that this localization is partially dependent on CXCR3 and CCR5 and differential expression of CXCR3 and CCR5 ligands." (PMID 29719539, 2018). "Interestingly, while expression kinetics of CXCR3 differed depending on the infection, peak expression of Lag-3 and CD85k occurred at similar time points in all three infections." (PMID 29951069, 2018). "Human Th1 cells specific for M. tuberculosis are largely contained in a CXCR3-expressing subset and in animal models it has been shown that CXCR3-expressing T cells are essential for containment of the infection during natural infection and by the T cells induced in experimental vaccines." (PMID 30026741, 2018). "Furthermore, animal studies have shown that CXCR3 enhances the ability of T cells to safeguard against infections." (PMID 29515587, 2018). "Additionally, we discovered a novel subpopulation of CD14+ monocytes associating with the acute phase of infection that expressed high levels of CCR4, CXCR3, and CCR6, among other markers." (PMID 30150281, 2018). "The results presented in this study strongly suggest that inhibition of mTORC1 activity in T cells upon rapamycin treatment decreases numbers of splenic effector T cells having the capacity to migrate into the brain (CD8+ CXCR3+) by day 6 of infection, a crucial step in ECM pathology." (PMID 29121917, 2017). "Although CXCR3−/− overtime eradicate infection is at the same pace as WT, this might be due to the contribution of another major IFN- resource: NK cells." (PMID 29552679, 2017). "This phenomenon resulted in recruitment of CXCR3-expressing T cells into the sites of infection." (PMID 28376103, 2017).
infection (continued). "Enhanced expression of chemokine receptors on lymphocytes (e.g. CXCR3) increases the transit of immune cells to sites of infection; meanwhile, higher expression of cellular adhesion molecules increases cell trafficking through the vascular endothelium to the site of infection." (PMID 28902848, 2017). "When compared to wild type (WT) mice, CXCR3 deficiency (CXCR3−/−) mice infected with Chlamydia muridarum (C. muridarum) did not display impaired clearance and resolution of infection." (PMID 29552679, 2017). "In order to determine the ability of CXCR3−/− mice to clear infections of Chlamydia, wild-type and knockout mice were infected with C. muridarum (CM), and the bacterial burden of these mice were measured every three days post infection using vaginal swabs." (PMID 29552679, 2017). "Our finding of a gradual increase of CXCR3 transcripts in the brains of lethal infection, but significantly higher expression levels in the brains of sublethal infection, is intriguing and warrants further investigation, as persistent infection can occur in human patients and mouse models." (PMID 28742087, 2017). "Given the marked elevation of transcripts for proinflammatory cytokines (IFN-γ and TNF-α) and T-cell recruiting signals (CXCL9 and CXCR3) in infected brains, we decided to focus on lethal infection, especially vascular/cellular activation and leukocyte recruitment." (PMID 28742087, 2017). "In macaques, we didn’t detect a higher rate of infection in CXCR3+ versus CXCR3neg CD4+ cells." (PMID 27509048, 2016). "At the same time, alternative subsets of cells may be the most relevant to mitigate the severity of an established infection, for example, those that express CXCR3, which may allow them to be selectively recruited to the site of infection." (PMID 26834750, 2016). "In particular, CXCR3 was found to be elevated on an increasing number of cells over the time course of infection and it was the primary chemokine receptor expressed at 60 days post infection." (PMID 27207308, 2016). "Modulations in the frequencies of CXCR3+ CD4+ T cells were observed upon infection." (PMID 27509048, 2016). "The different roles played by CXCR3 in different infection and different stages of the infections may be governed by the various expression of one of the two isoforms." (PMID 24472559, 2014). "CXCR3 and its ligands (CXCL9, CXCL10, and CXCL11) are undoubtedly linked to the Th1 pattern and constitute an inflammatory pathway that coordinates the immune responses at sites of infection and inflammation." (PMID 24586509, 2014). "Although the precise mechanism by which these chemokines contribute to human disease remains unclear, it is possible that their local production in the brain during infection might stimulate the accumulation of CXCR3+ and CCR5+ leucocytes." (PMID 24476686, 2014). "However, the total number of CD4+CXCR3−GFP− cells remained unchanged, further indicating that infection promotes the recruitment of CD4+CXCR3+ T cells." (PMID 24130498, 2013). "At day five post-infection, CXCR3 chemokines in serum correlate with morbidity and viral burden." (PMID 24324838, 2013). "Moreover, CXCL10 binds CXCR3 and enrolls Th1 cells to resist intracellular pathogen infection, such as viruses." (PMID 22906315, 2012). "Both CD4+ and CD8+ T cells from C57BL/6 mice up-regulated CXCR3 expression levels during infection." (PMID 19343215, 2009). "However, infection generates a higher proportion of IgA+ BSM and CXCR3+CD21+ BSM." (PMID 42173827, 2026). "In addition, the cytokine profile of the hypervirulent isolates in A/J mice had a profound IFNγ and IL-17 response, and lung resident CD4 T-cells isolated from A/J mice expressed significantly increased Th1 (CXCR3, Tbet) and Th17 (RORγT) markers compared with KN99α infection." (PMID 40029251, 2025).